SLC7A6OS (solute carrier family 7 member 6 opposite strand)
Description:
Directs RNA polymerase II nuclear import.
Synonyms: FLJ13291; Iwr1; EPM12
Tractability: PROTAC: ubiquitination databases record sites on it; its protein half-life has been measured.
Gene: Protein-coding gene on chromosome 16 (68,284,503 to 68,310,952, reverse strand). Ensembl gene ENSG00000103061.
Subcellular location: Cytoplasm; Nucleus
Subcellular location (Human Protein Atlas): Nucleoplasm; Cytosol
Gene Ontology:
Biological process: developmental process
Cellular component: cytoplasm; nucleus
Genetic constraint (gnomAD): Loss-of-function variants: 22 observed, 32.87 expected, observed/expected ratio (o/e) 0.67, 90% interval 0.48 to 0.96. The upper end of that interval is the gene's LOEUF score, 0.96, which puts it in group 4 of 6, group 1 being the genes least tolerant of losing a copy. Missense variants: 434 observed, 415.73 expected, observed/expected ratio (o/e) 1.04, 90% interval 0.96 to 1.13. Synonymous variants: 199 observed, 165.86 expected, observed/expected ratio (o/e) 1.2, 90% interval 1.07 to 1.35.
Homologues: Orthologues: chimpanzee SLC7A6OS (99% identical), macaque SLC7A6OS (96% identical), rabbit SLC7A6OS (83% identical), dog SLC7A6OS (82% identical), pig SLC7A6OS (81% identical), guinea pig SLC7A6OS (77% identical), rat Slc7a6os (76% identical), mouse Slc7a6os (76% identical), zebrafish slc7a6os (47% identical).
Diseases named in the same sentence as SLC7A6OS in open-access papers:
SLC7A6OS is named in the same sentence as 12 diseases in open-access papers, as found by Europe PMC text mining. Sharing a sentence is not in itself a finding about the gene and the disease.
SLC7A6OS shares sentences with these, for which no sentence is quoted: tumor (7 papers); cancer (3); breast carcinoma (2); colorectal cancer (2); glioma (2); infection (2); osteosarcoma (2); dysplasia (1); epilepsy (1); liver cancer (1); lung carcinoma (1); renal carcinoma (1).